IFNG (interferon gamma)
Diseases named in the same sentence as IFNG in open-access papers (continued):
Sharing a sentence is not in itself a finding about the gene and the disease.
tumor (continued). "We then hypothesized that the interferon gamma produced during anti-tumor immune responses would lead to the upregulation of PDL1, as this is an interferon gamma-induced gene." (PMID 30123214, 2018). "We found that concomitant transfer of HSCs with tumor-specific T-cells significantly increases tumor-specific T-cell activation and IFNγ secretion within the tumor microenvironment (p = 0.0110), and in draining lymph nodes relative to groups that received T-cells alone (p = 0.002)." (PMID 30333482, 2018). "In the meantime, the role of IFNγ signaling in tumor escape from immune elimination is discussed." (PMID 30039553, 2018). "To this end, we found that the activation of NK cells by either tumor stimuli or cytokines in the presence of TGFβ induces potent NK cell anti-tumor IFNγ and TNFα secretion and alterations in NK cell cytotoxicity, corresponding to the downregulation of T-bet and SMAD3 expression." (PMID 30400618, 2018). "T-cells secreted equal amounts of IFNγ when used as effectors against either the tumor-RNA-pulsed dendritic cells derived from CCR2+HSCs, or KR158B tumor cells themselves (p = 0.5176), demonstrating that CCR2+HSCs-derived cells have the capacity to present antigen on their MHC." (PMID 30333482, 2018). "In addition to the elevated CD8+ T-cell activation phenotypes, treated tumors also contained T-cell memory cells, evidence of increased tumor NK cell accumulation and cytolytic biomarkers and intratumoral IFNγ production." (PMID 30587236, 2018). "On the other hand, a wide range of pro-inflammatory factors, e.g., PGE2, TNF, IL-1β, IL-6, S100A8, S100A9, IFNγ, IL-4, IL-10, and IL-13 secreted by cancer cells and leukocytes residing in the tumor inhibit the differentiation of myeloid progenitors and enhance their suppressive capacity." (PMID 30349530, 2018). "Furthermore, the injection of IFNγ into tumours induced PD-L1 expression and promoted tumour growth, while PD-L1 inhibition abrogated tumour growth." (PMID 29707124, 2018). "PD-L1 expression can also be up-regulated in the tumor microenvironment as a result of immune activation and production of pro-inflammatory cytokines such as interferon-gamma (IFNγ), contributing to the establishment of an “adapted” T-cell immunosuppressive milieu." (PMID 29712568, 2018). "Lymphocytes in the TLSs could be educated by T-DC immunization, and the presence of TLSs could suppress MC38 tumor growth accompanied by enhanced IFNγ release of TILs and downregulation of their expression of checkpoint inhibitors PD-1 and Tim-3." (PMID 30061886, 2018). "CAR33VH and My96CAR elaborated high levels of IFNγ, TNFα, and IL-2 in response to CD33high tumor lines MOLM-14 and HL-60, whereas CAR T-secreted cytokines were not significantly induced when challenged with CD33moderate line KG-1a, or CAR T cells incubated alone, demonstrating antigen specificity." (PMID 30524966, 2018). "LNT inhibits tumor angiogenesis by increasing IFNγ production and in a T cell-independent manner." (PMID 30373628, 2018). "As IFNγ is critical for CTLs to exert their tumor killing activities, this pharmacological epigenetic modifier could potentially be used to enhance the efficacy of cancer vaccines." (PMID 30740111, 2018). "Increased splenic volume and induction of IFNγ mRNA following IL-12-LNP treatment suggest that IL-12 may potentially induce anti-tumor immunological changes." (PMID 30458889, 2018). "Importantly we further confirmed that there were significantly increased tumor infiltrating lymphocyte (TIL) populations in the lung by CD45 staining which contains IFNγ producing T cells with increased Th1 and CTL related mRNA expression in tumor region." (PMID 29403003, 2018).
tumor (continued). "Tumor cells can also evolve immune escape mechanisms blocking the IFNγ pathway." (PMID 30026743, 2018). "Other groups have instead reported the pro-tumor role exerted by neutrophils in promoting metastasis formation through the decrease of IFNγ production, the secretion of the vasculature remodelling protein MMP9 and the secretion of neutrophil-derived leukotrienes." (PMID 30333826, 2018). "Furthermore, treatment of tumor-free, immunocompetent animals resulted in increased NK cell killing activity, increased degranulation and increased IFNγ production upon ex vivo stimulation." (PMID 29304125, 2018). "The blockade of IFNγ using a specific antibody or the use of CCR2 deficient mice, which were subjected to UVB exposure, have decreased of macrophages infiltration in the skin and reduced tumor volume." (PMID 30420855, 2018). "Moreover, following the stimulation, Th1 cells produce IFNγ that in turn increase antigen presentation on cancer cells, to enhance direct killing of tumor cells as well as create an immunogenic tumor microenvironment, thus further helping tumor control." (PMID 30740111, 2018). "In addition to well‐known functions, IFNγ signaling also induces tumor ischemia and homeostasis program, resulting in tumor clearance and tumor escape, respectively." (PMID 30039553, 2018). "KR158B tumor cells were used as a positive target control, and supernatant IFNγ was then measured." (PMID 30333482, 2018). "B220+CD11c+NK1.1+ cells were originally reported as NK cells with high expression of IFNγ in lymphoid organs, and they may circulate in several organs during tumour progression." (PMID 29930175, 2018). "The IFNG-committed Th1 compartment is the most prominent of the four T cell lineages examined here, indicating that Th1 is the major lineage response towards the tumour, which is in agreement with the literature." (PMID 30075815, 2018). "In addition, LNT treatments (1.0 mg/kg) up-regulated IFNγ production in several tumor-infiltrating myeloid cell populations." (PMID 30373628, 2018). "IFNγ also plays a critical function in cancer immunosurveillance as it can be secreted in the tumor micro-environment, determining the inflammatory status of the tumor and influencing tumor prognosis." (PMID 30026743, 2018). "Paradoxically, IFNγ also trigger TIL apoptosis by inducing PDL1 expression in the tumor microenvironment, which causes to a negative-feedback that eventually inhibits antitumor immunity." (PMID 30409126, 2018). "This may occur through production of pro-inflammatory cytokines such as IFNγ from T-cells within the tumor microenvironment." (PMID 29805749, 2018). "In addition, IFNγ decreases tumor cell growth by inducing tumor cell cycle arrest, apoptosis and necroptosis." (PMID 30039553, 2018). "Finally, radiation can induce MHC-I expression on cancer cells, either by an accumulation of damaged proteins and their break-down products, or in response to a general increase of IFN gamma (IFNγ) within the tumor microenvironment." (PMID 30692993, 2018). "Hazard ratio (HR) and 95% confidence interval (95% CI) for 5-yeras disease free survival (DFS) and overall survival (OS) in the pooled group of patients according to an increasing number of clinical (gender, tumor site and stage) and genetic (MTHFR-rs1801131, IFNG-rs1861494) risk factors." (PMID 30337874, 2018). "Additionally, we observed that IL-12-LNP treatment of HCC-bearing mice significantly upregulated the production of IFNγ mRNA in the normal liver tissue surrounding the tumor when compared to NST-LNP treated controls." (PMID 30458889, 2018). "γδ T cells were shown to efficiently kill tumor cells by releasing perforins, granzymes and IFNγ." (PMID 30333826, 2018).
tumor (continued). "Conversely, in anti-tumour immunity, the high expression of IFNγ in the tumour milieu dictates high-endothelial expression of CX3CL1 that overrides the action of chemokines required for HPMo transmigration, thus imposing a state of continuous crawling for proangiogenic monocytes in the vessel lumen." (PMID 29367702, 2018). "Interestingly, the injection of CD8+ cultured in Th9 skewing conditions (IL-4, TGF-β, and anti-IFNγ) was shown to give rise to Tc9 with stronger anti-tumor tumor effects than IFN-γ cytolytic CD8+ T cells in pre-clinical cancer models." (PMID 29891791, 2018). "On the other hand, anti-tumor populations are characterized by IFNγ producing γδ T cells." (PMID 30538697, 2018). "However, loss of MHC class I in DFT1 is reversible upon treatment with the inflammatory cytokine IFNγ and a small number of individuals have been found to have a successful immune response against the tumour." (PMID 30103855, 2018). "Importantly, a pharmacodynamic biomarker of tumor rejection was identified by coordinated elevations in serum IFNγ, IL-2, IL-4, IL-5, IL-6 and IL-17A." (PMID 30400822, 2018). "Conversely, the selective activation of Dll1-mediated Notch signaling in BM precursors in tumor-bearing mice resulted in the increase of tumor-infiltrating T cells and enhanced activation of Th1-type IFNγ-producing T cells, resulting in tumor growth inhibition." (PMID 30154786, 2018). "Moreover, NKG2D receptor on NK cells binds to MICA, one of its ligands, on monocytes that reside in the tumor microenvironment, boosting NK cell antitumor activity against Ab-coated tumor cells and ultimately increasing their production of interferon-γ (IFNγ)." (PMID 29403144, 2017). "The percentage of total CD8s that were antigen specific and capable of producing IFNγ and TNFα was 5 to 15% in spleens and 5 to 15% in tumors, respectively, indicating significant expansion of antigen-specific lymphocytes in the tumor and the peripheral reservoir." (PMID 28649380, 2017). "For instance, IFNγ has been shown to elevate in the tumour stroma." (PMID 29156701, 2017). "In further support, BRAFV600E inhibitor treatments have been associated with dendritic cell maturation, increased expression of co-stimulatory molecules including CD40L, production of IFNγ, TNFα and IL-12, and moderate enhancement of circulating tumor antigen-reactive CD8+ T cells." (PMID 29100459, 2017). "Hence, galectin-3 retains IFNγ in the tumor microenvironment, thereby decreasing the extension of a CXCL9 gradient." (PMID 28986561, 2017). "According to our data, the ligands most upregulated by IFNγ were PD-L1, ICAM-1, and MHC-class I; therefore, we determined whether changes in their expression correlated to changes in tumor lysis after IFNγ treatment." (PMID 28428785, 2017). "Moreover, vaccines can increase tumor-infiltrating CD8+ T cells that secrete IFNγ, leading to upregulation of the PD1–PDL1 pathway and other inhibitory pathways and creating a negative feedback loop that can suppress tumor immunity." (PMID 29234329, 2017). "Since the CD3xPDL1 BiTE targets PDL1+ cells, it may also minimize PD1 pathway immune suppression that is likely to escalate as T cell anti-tumor immunity and levels of IFNγ increase in the tumor microenvironment." (PMID 28938530, 2017). "Interestingly, inhibition or depletion of SHP2 in tumor cell lines or treatment with IFNγ induced upregulation of phosphorylated STAT1 (pSTAT1) and restored expression of HLA class I and APM components." (PMID 28611673, 2017). "Although TNFα and IFNγ both increased PD-L1 expression (4202 ± 2500 and 4724 ± 4155, respectively), it was only the combination TNFα/IFNγ (25818 ± 14131, p < 0.0001) that resulted in a significant increase in PD-L1 expression in tumor-derived Lin-EpCAM-CD73+CD90+ cells." (PMID 28878242, 2017).
tumor (continued). "The effectiveness of Th1 cells in the generation and maintenance of strong immunological memory has been shown, as well as association between secretion of IFNγ by CD4 T cells and their anti-tumor effects, e.g. by reducing proliferation and angiogenesis and enhancing apoptosis of tumor cells." (PMID 28183282, 2017). "Moreover, there are reports of IFNγ being pro-tumorigenic even though its inhibiting tumour growth was only evident at a much high dose." (PMID 29156701, 2017). "We wondered whether the increased T-cell infiltration and activation phenotype observed in tumors injected with IFNγ and galectin antagonists would have an impact on tumor growth." (PMID 28986561, 2017). "The BiTE induced high levels of IFNγ in the PBMC + BiTE + tumor cell samples." (PMID 28938530, 2017). "Interestingly, proliferation of both tumor cell lines was significantly reduced when cultured in CM of IFNγ- and TNFα-activated microglia (p < 0.001, ratios 0.51 and 0.49), but not by TGFβ1-treated microglial CM (ratios 0.98 and 1.05)." (PMID 28008153, 2017). "CD8+ effector T cells can directly kill tumor cells by releasing perforin, granzyme B and IFNγ." (PMID 28220815, 2017). "A detailed study revealed that local IFNγ could directly target tumour vascular endothelial cells and affect tumour stroma." (PMID 29156701, 2017). "TRTC responses against own-tumor antigens were evaluated by IFNγ production." (PMID 29190690, 2017). "Moreover, the anti-tumor effect of αGalCer is potentially mediated by IFNγ- and TNFα-producing NKT1 cells." (PMID 29312339, 2017). "In melanoma patients, LDHA expression correlated with T cell activity and LDHA-associated lactic acid production and acidification impaired IFNγ expression in tumor-infiltrating T cells and NK cells, thereby inhibiting tumor immunosurveillance and promoting tumor growth." (PMID 28337200, 2017). "Interestingly, IFNγ, which restored of HLA class I expression and antigen presentation in tumor cells is also a major inducer of PD-L1 expression as shown in multiple cancer types including HNSCC, fibrosarcoma, glioblastoma, and multiple myeloma cells." (PMID 28611673, 2017). "The IRF1-mediated IFNγ signaling pathway regulates MHC class I antigen presentation in tumor cells." (PMID 28977839, 2017). "This indicates that bortezomib can activate alternative pathways leading to IFNγ production that could strengthen tumor immune surveillance." (PMID 28052005, 2017). "Likewise, SHP2-mediated pSTAT1 downregulation diminished the production of Th1 cytokines by tumor cells, since its inhibition induced increased secretion of interleukin-12 (IL-12) p35/p40 and IFNγ-dependent CXCR3 and CCR5 binding chemokines." (PMID 28611673, 2017). "This enzyme, whose expression can be induced by IFNG, is centrally involved in the degradation of tryptophan in tumor cells whose depletion eventually results in cell cycle arrest and apoptosis of T-cells, thus possibly supporting PD-L1 CNG tumors to escape immune surveillance." (PMID 29212506, 2017). "Also, this study showed that ASCs have immune modulatory properties that enhance the effects of IFNγ in the tumor microenvironment." (PMID 29181035, 2017). "Moreover, the release of interferon gamma (IFN-γ) by TILs can directly induce PD-L1 expression in tumor cells and immune cells." (PMID 28076847, 2017). "Furthermore, γδT17 cells can promote tumor progression, whereas interferon-γ (IFNγ)-producing γδ T (γδT1) cells have potent anti-tumor activity." (PMID 29222418, 2017). "CXCL9 mRNA was measured in each section along the whole tumor, as a read-out of IFNγ signal." (PMID 28986561, 2017). "Here, we evaluated if modulation of PDL1 expression on various tumor cell lines could alter PHA-stimulated activation of healthy donor PBMC as measured by intracellular expression of IFNγ or release of IFNγ into the supernatant." (PMID 28325288, 2017).
tumor (continued). "In CAR T-cell therapy, this feedback loop may provide a means of replicating the “inflamed” immunophenotype of tumours enriched in IFNγ due to DC-mediated antigen presentation to CD4+ and CD8+ T-cells." (PMID 29157300, 2017). "To address this, following tumor inoculation we measured global cytokine mRNA differences, including TGFβ, TNFα, IL-10 and IFNγ, between WTTU and L3TU groups on day 5, the time point where we observed the greatest differences in cellular accumulation and CD69 positivity." (PMID 29109732, 2017). "On the other hand, NK cells might also be detrimental for avoiding PD1 blocking since IFNγ derived from tumor-infiltrating NK cells may further increase the expression of the ligand PD-L1 in the tumor microenvironment." (PMID 28348567, 2017). "IFNγ-resistant tumour cells are protected from cytokine-induced growth inhibition and apoptosis." (PMID 28561041, 2017). "Mice and cells lacking IFNγ display compromised tumor rejection, underlining its importance in tumor surveillance." (PMID 28184222, 2017). "As microglia treated by IFNγ and TNFα supposedly represent a population of M1 activated microglia and TGFβ1 treated cells a subpopulation of M2 activated microglia, the tumor cells in our experimental system seem to shift microglia towards a more M2-like phenotype." (PMID 28008153, 2017). "Occupation of the IL-12 receptor on T and NK cells induces STAT4 phosphorylation, leading to expression of IFNγ, a crucial activator of macrophages and class II major histocompatibility complex gene expression and thus an essential player in tumor surveillance." (PMID 28275576, 2017). "Nevertheless, the increased numbers of tumor-infiltrating CD8+ T cells correlate with a better survival prognosis, suggesting that TILs maintain their functionality at least partially as suggested by increased levels of IFNγ in tumor tissue from patients with a favorable clinical outcome." (PMID 28275576, 2017). "It has also been reported that after undergoing primary tumor excision and/or immunotherapy and presenting a disease-free period, IFNγ-producing type-1 CD4+ T cells prevail in RCC patients, suggesting that tumor environment may promote a type-2 response." (PMID 28409322, 2017). "We examined whether galectin-3 was able to modulate IFNγ-induced CXCL9 expression in human tumor cells." (PMID 28986561, 2017). "Furthermore, epitope-specific stimulation of TCR-transduced T cells by peptide- or whole tumor lysate-loaded DC was efficiently stimulated only by DC matured in the full maturation cocktail containing IFNγ and the three TLR ligands R848, poly I:C, and LPS." (PMID 28601925, 2017). "BCG-injected lesions presented increased transcripts levels of (among others) HLA-A, IFNG, PD1, and 4-1BB, a finding compatible with the enhanced production of IFN-γ observed on HLA-A2-restricted TILs challenged with HLA-A2+ tumor cells preexposed to BCG in vitro." (PMID 28848560, 2017). "Also we evaluated the effects of IFNγ treatment on tumor expression of NK cell ligands, including activating and inhibitory ligands, death receptors, and adhesion molecules." (PMID 28428785, 2017). "Opposing effects reported for IFNγ may be due to a focus on specific tumor types, therefore this study aimed to evaluate the effect of IFNγ on a broad selection of 22 tumor cell lines from the pediatric preclinical testing program (PPTP) in vitro panel." (PMID 28428785, 2017). "Moreover, the Vax/aGITR/aPD-1 therapy showed a synergistic effect, as illustrated by the higher frequency of OVA-specific IFNγ/TNFα dual-positive CD8+ T cells within the tumor." (PMID 28388572, 2017). "PDL1+ tumor cells (MDA-MB-231BR cells infected with RRV-miRGFP) in the presence of an anti-PDL1 blocking antibody were unable to suppress CD8+ T cell activation as indicated by the increased frequency of IFNγ+/CD8+ T cells." (PMID 28325288, 2017).